GP1BA (glycoprotein Ib platelet subunit alpha)
Description:
GP-Ib, a surface membrane protein of platelets, participates in the formation of platelet plugs by binding to the A1 domain of vWF, which is already bound to the subendothelium.
Synonyms: GPIbA; CD42b; HPA-2; GPIbalpha; BDPLT1; BDPLT3; BSS; CD42b-alpha; DBPLT3; GP1B; VWDP
Tractability: Small molecule: a structure with a bound ligand is known. Antibody: its Gene Ontology location is reachable by antibodies, with high confidence; UniProt predicts a signal peptide or a membrane-spanning region. Other modalities: a drug acting on it is in phase 2 or 3 trials.
Gene: Protein-coding gene on chromosome 17 (4,932,277 to 4,935,023, forward strand). Ensembl gene ENSG00000185245.
Subcellular location: Membrane
Pathways (Reactome):
Hemostasis: Amplification and propagation of coagulation cascade; FXIIa, PKa-dependent activation of coagulation pathway; GP1b-IX-V activation signalling; Platelet Adhesion to exposed collagen; Platelet Aggregation (Plug Formation); Regulation of clotting cascade
Disease: Defective F9 activation; Defective binding of VWF variant to GPIb:IX:V; Enhanced binding of GP1BA variant to VWF multimer:collagen
Gene expression (Transcription): RUNX1 regulates genes involved in megakaryocyte differentiation and platelet function
Gene Ontology:
Molecular function: protein binding; signaling receptor activity; thrombin-activated receptor activity
Biological process: blood coagulation; blood coagulation, intrinsic pathway; cell adhesion; fibrinolysis; positive regulation of platelet activation; release of sequestered calcium ion into cytosol; cell surface receptor signaling pathway; megakaryocyte development; platelet activation; regulation of blood coagulation; thrombin-activated receptor signaling pathway
Cellular component: cell surface; external side of plasma membrane; extracellular exosome; glycoprotein Ib-IX-V complex; membrane; plasma membrane
Genetic constraint (gnomAD): Loss-of-function variants: 4 observed, 7.06 expected, observed/expected ratio (o/e) 0.57, 90% interval 0.28 to 1.29. That is too few expected variants to judge how well the gene tolerates losing a copy. Missense variants: 701 observed, 814.4 expected, observed/expected ratio (o/e) 0.86, 90% interval 0.81 to 0.92. Synonymous variants: 321 observed, 362.74 expected, observed/expected ratio (o/e) 0.88, 90% interval 0.81 to 0.97.
Gene-disease validity (ClinGen):
ClinGen rates the evidence that GP1BA causes each of these diseases.
Bernard-Soulier syndrome (autosomal recessive): Definitive. Bernard Soulier syndrome (BSS) is an inherited platelet disorder characterized by mild to severe bleeding tendency, macrothrombocytopenia and absent ristocetin-induced platelet agglutination.
platelet-type von Willebrand disease (autosomal dominant): Definitive. A bleeding disorder characterized by mild to moderate mucocutaneous bleeding, which becomes more pronounced during pregnancy or following ingestion of drugs that have anti-platelet activity.
Homologues: Orthologues: chimpanzee GP1BA (99% identical), mouse Gp1ba (62% identical), rat Gp1ba (61% identical), rabbit GP1BA (55% identical). Paralogues in human: FLRT1 (17% identical), FLRT3 (17% identical), FLRT2 (16% identical), LRRC15 (14% identical), LRRC4 (14% identical), LRRTM3 (14% identical), LRRTM4 (14% identical), RTN4R (13% identical), LRRC4C (13% identical), RTN4RL2 (13% identical), LRRC66 (13% identical), LRRTM1 (13% identical), and 10 more.
Diseases named in the same sentence as GP1BA in open-access papers:
GP1BA is named in the same sentence as 138 diseases in open-access papers, as found by Europe PMC text mining. Sharing a sentence is not in itself a finding about the gene and the disease. The quoted sentences say what the papers report.
Thrombocytopenia (41 papers, 2012 to 2025). A reduction in the number of circulating thrombocytes. "Previous studies have shown homozygous or heterozygous variants in GP1BA can cause severe thrombocytopenia, giant platelets and a bleeding tendency." (PMID 41340014, 2025). "Thrombocytopenia can be induced in mice by intravenous injection of anti-CD42b (anti-GP1ba) antibody." (PMID 37279077, 2023). "Among these, GP1BA (c.1591dup, c.1525C>T, and c.378C>G), ITGB3 (c.1394C>G), NBEAL2 (c.3796del), WAS (c.655G>T, deletions of exons 1-2), and MPL (c1511T>A) were notable for their association with severe thrombocytopenia and morphological platelet abnormalities." (PMID 40488176, 2025). "We found that GP1BA-, MYH9-, ACTN1-, and ANKRD26-related thrombocytopenias are the most frequent diseases diagnosed with a highly variable clinical course and long-term prognosis." (PMID 36507135, 2022).
Stroke (18 papers, 2011 to 2025). Sudden impairment of blood flow to a part of the brain due to occlusion or rupture of an artery to the brain. "Studies performed in stroke patients revealed that genetic alterations in the GP1bA gene and increased serum levels of vWF are risk factors for stroke, and a predictive factor for long term mortality after acute stroke." (PMID 31736950, 2019). "In male patients, four of the 34 SVD-associated genes were unique to that specific stroke cause: CYP4F2, GP1BA, solute carrier family four, member one (SLC4A1), and F13A1, which was also uniquely expressed in the male cohort." (PMID 33193047, 2020). "Apart from pathogenic or likely pathogenic findings, 41 rare VUS in 325 stroke-related candidate genes were detected in 39 probands, including eight novel variants: ABCA1 p.H1223P, ACTA2 p.N298S, COL5A1 p.P930R, FBN1 p.Q514E, FBN1 p.K1052T, GP1BA p.P437*, RNF213 p.N1631Efs*34, and TSC1 p.P397del." (PMID 36580209, 2023). "Weaker evidence was found for GP1BA, VCAM1 and LAMC2 as potential drug targets for stroke, with evidence for colocalization in only one pQTL dataset." (PMID 36180795, 2022). "GP1BA and angiopoietin-1 (ANGPT1) negatively correlated with time after stroke in females at the gene level." (PMID 33193047, 2020). "Using public drug databases, we curated drugs targeting those proteins in a direction compatible with a beneficial therapeutic effect against stroke based on MR estimates and identified such drugs for VCAM1, F11, KLKB1, GP1BA, LAMC2 (inhibitors) and PROC (activators)." (PMID 36180795, 2022).
Macrothrombocytopenia (15 papers, 2006 to 2025). "A germline GP1BA gene variant (NM_000173:c.98G > A:p.C33Y), segregating with the macrothrombocytopenia, was detected by whole-exome sequencing." (PMID 35055070, 2022). "According to several studies, we detected that in most patients, the mutation of GP1BA is exclusively associated with a macrothrombocytopenia." (PMID 36507135, 2022). "WES identified a heterozygous variant within GP1BA exon 2 (NM_000173:c.98G > A:p.C33Y) in both affected family members with macrothrombocytopenia (II-1; II-2)." (PMID 35055070, 2022). "The heterozygous variant within GP1BA exon 2 (NM_000173:c.98G > A:p.C33Y) was also found in a third family member with macrothrombocytopenia (III-1) by Sanger sequencing." (PMID 35055070, 2022). "We report a germline heterozygous variant c.98G > A leading to substitution of p.C33Y in the GP1BA gene, segregating with macrothrombocytopenia in two generations." (PMID 35055070, 2022). "Although individuals with only one mutant allele are overwhelmingly asymptomatic carriers, approximately 2% of them, primarily those with a GP1BA mutation, can have a mild macrothrombocytopenia that is transmitted as an autosomal dominant trait." (PMID 33553065, 2020). "The GPIbα-deficient (Gp1ba-/-) mice presented the typical macrothrombocytopenia phenotype." (PMID 34657146, 2021). "Since Gp1ba−/− mice displayed severe macrothrombocytopenia, to distinguish the role of GPIbα in metastasis, Mpl−/− mice, which have low platelet counts but normal GPIbα expression in the platelets, were selected." (PMID 40491968, 2025). "Moreover, rare variants in the GP1BA and GP1BB genes have been reported in patients with macrothrombocytopenia and the AD (monoallelic) mode of inheritance, presenting with a mild, usually asymptomatic form." (PMID 35055070, 2022). "Examples include: BSS (GP1BA, GP1BB, GP9 genes); platelet-type von Willebrand disease (GP1B1); GT (ITGA2B and ITGB3); MYH9-RD if there is macrothrombocytopenia, Döhle bodies, and/or typical extra hematologic manifestations (MYH9)." (PMID 40563486, 2025). "In contrast, macrothrombocytopenia, even with giant platelets, is typical of alterations in the GP1BA, GP1B, GP9, MYH9, SRC, and SLFN14 genes, and in the majority of ITs from variants in genes that encode cytoskeletal proteins or participate in glycosylation." (PMID 40563486, 2025).
ischemic stroke (11 papers, 2011 to 2024). A stroke disorder caused by obstruction of blood flow to the brain, due to thrombotic (local blood clot formation) or embolic (due to a blood clot or other material traveling from another site) event. "Here, we report the mBSS patient (II-1) with two previous ischemic strokes despite heterozygous GP1BA variant and reduction of GPIbα-IX-V complex expression." (PMID 35055070, 2022). "(Mother (I-2) of this patient had five ischemic strokes before she died, but the GP1BA status is due to the lack of DNA sample unknown)." (PMID 35055070, 2022).
Bernard-Soulier syndrome (10 papers, 2016 to 2025). "Reduced platelet numbers from GP1BA-deficient cells were accompanied by increased cell size, as apparent by IF analysis and flow cytometry, recapitulating the platelet phenotype of the Bernard-Soulier syndrome." (PMID 40775216, 2025). "Bernard-Soulier Syndrome: GP1BA, GP1BB, or GP9 genes cause a disorder of large platelets." (PMID 40822568, 2024). "Bernard-Soulier syndrome (BSS; MIM #231200) is a rare autosomal-recessive bleeding disorder caused by biallelic variants in the GP1BA, GP1BB, and GP9 genes that encode the subunits GPIbα, GPIbβ, and GPIX, respectively, of the GPIb-IX receptor complex." (PMID 34638529, 2021). "Bernard-Soulier syndrome (BSS) is an autosomal-recessive bleeding disorder caused by biallelic variants in the GP1BA, GP1BB, and GP9 genes encoding the subunits GPIbα, GPIbβ, and GPIX of the GPIb-IX complex." (PMID 34638529, 2021). "Genetic knock-out studies in Hoxa7-TPO cells recapitulate the key function of Klf1 and Nfe2 in red blood cell and platelet development, respectively, while disruption of the von Willebrand receptor gene Gp1ba recapitulates features of human Bernard-Soulier syndrome." (PMID 40775216, 2025).
Arterial thrombosis (9 papers, 2015 to 2026). The formation of a blood clot inside an artery. "GP1BA encodes a platelet surface membrane protein and can affect arterial thrombosis-mediated platelet counts." (PMID 37211158, 2023).
Von Willebrand disease (9 papers, 2015 to 2024). von Willebrand disease (VWD) is a hereditary bleeding disorder caused by a genetic anomaly leading to quantitative, structural or functional abnormalities of the Willebrand factor (von Willebrand factor; VWF). "As another example of a CE-specific DV identification, we identified the M255V variant of the platelet glycoprotein Ib alpha chain (GP1BA), which is associated with pseudo-von Willebrand disease (VWDP)." (PMID 31199866, 2019). "Platelet-type von Willebrand disease (PT-VWD), is also caused by rare mutations (only five reported) in the GP1BA gene." (PMID 33926054, 2021). "von Willebrand factor can interact with osteoprotegrin to regulate osteoclast differentiation, and a transgenic GP1BA von Willebrand disease model has increased bone mass and reduced osteoclast activity." (PMID 26023928, 2015).
thrombosis (8 papers, 2015 to 2024). "Genetic variants of GP1BA may be associated with venous thrombosis in Asian ancestry." (PMID 36959823, 2023).
atherosclerosis (6 papers, 2016 to 2026). A disease characterized by the build-up of fatty material and calcium deposition in the arterial wall resulting in partial or complete occlusion of the arterial lumen. "LC-MS/MS-based serum proteomic analysis of Atherosclerosis (AS) and Anaphylaxis (AP) mice identified fibronectin 1 (FN1), platelet glycoprotein Ibα chain (GP1BA), and platelet factor 4 (PF4) as candidate biomarkers." (PMID 41828395, 2026).
lung carcinoma (6 papers, 2018 to 2025). "Druggability evaluation suggests that existing drugs targeting ITGB2, GP1BA, ACADSB and COX6B1 could potentially be repurposed for the treatment of specific lung cancer subtypes." (PMID 41340014, 2025). "Additionally, the repurposing of approved drugs targeting ITGB2, GP1BA, ACADSB and COX6B1 for the treatment of different lung cancer subtypes provides new therapeutic options, potentially leading to more effective treatments for patients with advanced lung cancer." (PMID 41340014, 2025).
asthma (3 papers, 2021 to 2025). "Among these pathways, hematopoietic cell lineage is closely related to asthma, and the mRNAs enriched in this pathway included FCER2A, GP1BA, IL-7, and CD5." (PMID 34737744, 2021).
bleeding disorder (3 papers, 2014 to 2022). "Bernard–Soulier syndrome (BSS) is an extremely rare (1: 1,000,000) bleeding disorder of platelet adhesion, caused by defects in the glycoprotein genes GP1BA (encoding GPIbα), GP1BB (encoding GPIbβ) and GP9 (GPIX) with autosomal recessive inheritance pattern." (PMID 25275492, 2014).
Hypertension (3 papers, 2020 to 2024). The presence of chronic increased pressure in the systemic arterial system. "Similarly, GP1BA associated with body mass index, metabolic syndrome, and hypertension in KORA (p = 6.66 × 10−6–3.72 × 10−4)." (PMID 31900413, 2020).
Splenomegaly (3 papers, 2023). Abnormal increased size of the spleen. "Nlrp3A350V/+/Gp1ba-CreKI/+ mice had mild anemia, reduced Ter119+ cells in the bone marrow, and splenomegaly." (PMID 37622117, 2023).
adenoma (2 papers, 2024 to 2025). A neoplasm arising from the epithelium. "Several interactions only occurred in specific locations, such as signalling pathways of CALCR, RANKL and TWEAK in the submucosa, GDNF, GDF, IL12, CD30 and CD137 signalling pathways in the adenoma, and PD‐L1, GP1BA, RESISTIN and SPP1 signalling pathways in tumour." (PMID 39934971, 2025).
allergic disease (2 papers, 2023 to 2024). An immune response that occurs following re-exposure to an innocuous antigen, and that requires the presence of existing antibodies against that antigen. "The objective of this study is to investigate the potential association between gene polymorphisms in GP1BA rs6065, PEAR1 rs12041331, and PAI-1 rs1799762 and the levels of serum specific-IgE (sIgE) and blood eosinophils in Chinese patients with allergies." (PMID 38299390, 2024). "The HWE equilibrium law was followed by the frequency distributions of the following polymorphisms in allergy patients: CYSLTR1 rs320995, GSDMB rs7216389, GPIIIa rs5918, GP1BA rs6065, PEAR1 rs12041331, PAI-1 rs1799762, and TNF-α rs1800629 (p > .05)." (PMID 36911417, 2023). "In conclusion, our study found that the GP1BA rs6065, PEAR1 rs12041331, and PAI-1 rs1799762 polymorphisms may be associated with the genetic susceptibility of serum sIgE or blood eosinophil in Chinese allergic disease patients." (PMID 38299390, 2024). "Based on the results of this study, it can be concluded that the GP1BA rs6065, PEAR1 rs12041331, and PAI-1 rs1799762 polymorphisms may be associated with the genetic susceptibility of serum sIgE or blood eosinophil in Chinese allergic disease patients." (PMID 38299390, 2024).
anaphylaxis (2 papers, 2020 to 2022). An acute hypersensitivity reaction that occurs from exposure to an allergen. "Of particular interest, ectodomain shedding results in rapid downregulation of platelet receptors such as GP1BA, which our analysis showed to be downregulated at the genetic level during severe anaphylaxis." (PMID 36583159, 2022). "Seven genes (TLN1, GATA1, SELP, GP1BA, MPL, F13A1 and SPARC) were also downregulated in patients with severe anaphylaxis who did not receive adrenaline before ED arrival, compared with healthy controls." (PMID 36583159, 2022).
cognitive decline (2 papers, 2021 to 2025). "Further machine learning analysis revealed that a combination of four decreased platelet proteins, that is, PHB, UQCRH, GP1BA, and FINC, was most promising for predicting cognitive decline in MCI and AD patients." (PMID 33942972, 2021). "Together, the machine leaning further selects out the combination of PHB, UQCRH, GP1BA, and FINC as the best platelet biomarkers for evaluating the cognitive decline in MCI and AD patients." (PMID 33942972, 2021). "Further PLS‐DA analysis plus machine learning revealed that a combination of decreased proteins PHB, UQCRH, GP1BA, and FINC in platelets could be promising in objectively predict the cognitive decline in MCI and AD patients." (PMID 33942972, 2021).
juvenile idiopathic arthritis (2 papers, 2021). Juvenile idiopathic arthritis (JIA) is the term used to describe a group of inflammatory articular disorders of unknown cause that begin before the age of 16 and last over 6 weeks. "As one example, the platelet glycoprotein Ib alpha chain is a platelet surface membrane protein encoded by the GP1BA gene, which could influence the risk of juvenile idiopathic arthritis and atherothrombosis mediated platelet counts." (PMID 34561445, 2021).
squamous cell carcinoma (2 papers, 2024 to 2025). A carcinoma arising from squamous epithelial cells. "Tier 1 proteins passed all evaluations, including GP1BA (squamous cell carcinoma) and ACADSB (small cell carcinoma)." (PMID 41340014, 2025). "Additionally, we found that DPP10 (Log2FC = 1.08, pFDR = 0.007) and GP1BA (Log2FC = −1.21, pfdr = 1.24 × 10−11) exhibited significantly different expression between squamous cell carcinoma and normal tissues." (PMID 41340014, 2025).
steatosis (2 papers, 2022 to 2025). Increased lipid within the cytoplasm of cells. "Specifically, H4C1, OIT3, ANPEP, CCDC25 and KLHL41 were identified as potential biomarkers for steatosis, GP1BA as a candidate marker for MASH and C7, IGHD and GNB1 as potential biomarkers for fibrosis severity." (PMID 41301514, 2025).
autism (1 paper, 2025). Persistent deficits in social interaction and communication and interaction as well as a markedly restricted repertoire of activity and interest as well as repetitive patterns of behavior. "Patient 13, who exhibited BSS due to a novel homozygous GP1BA variant, also presented with autism and intellectual disability, findings not typically associated with this disorder." (PMID 40488176, 2025).
autosomal dominant macrothrombocytopenia (1 paper, 2021). This syndrome is characterized by congenital thrombocytopenia associated with the presence of large platelets. "However, a limited number of variants in the GP1BA or GP1BB genes have been previously associated with mild autosomal-dominant macrothrombocytopenia; of note, most of these variants have been implicated in classical biallelic BSS when present in homozygosis or compound heterozygosis." (PMID 34638529, 2021).
bile acid synthesis disorder (1 paper, 2025). "Druggability evaluation highlighted four protein biomarkers, ITGB2, GP1BA, ACADSB and COX6B1, which are already targeted for dry eye disease, inflammation, seizure and bile acid synthesis disorder, respectively." (PMID 41340014, 2025).
Cognitive impairment (1 paper, 2021). Abnormal cognition is characterized by deficits in thinking, reasoning, or remembering. "Machine learning identified distinctive cognitive impairment‐platelet combination biomarkers (PHB, UQCRH, GP1BA, and FINC)." (PMID 33942972, 2021).
coronary atherosclerosis (1 paper, 2026). Atherosclerosis of the coronary vasculature. "In airway epithelium, FN1 was upregulated in anaphylactic sudden death (ASD) and anaphylactic sudden death (ASD) with Coronary Atherosclerosis (ASD + CAS) groups, while GP1BA was downregulated." (PMID 41828395, 2026).
Gastrointestinal hemorrhage (1 paper, 2025). Hemorrhage affecting the gastrointestinal tract. "Similarly, defects in VWF type 2B or GP1BA compromise platelet adhesion or function, elevating the risk of gastrointestinal hemorrhage." (PMID 40488176, 2025).